SPECC1 (sperm antigen with calponin homology and coiled-coil domains 1)
Synonyms: NSP5; CYTSB; HCMOGT-1; FLJ36955; NSP; HCMOGT1
Tractability: PROTAC: ubiquitination databases record sites on it; its protein half-life has been measured.
Gene: Protein-coding gene on chromosome 17 (20,008,865 to 20,319,026, forward strand). Ensembl gene ENSG00000128487.
Subcellular location: Nucleus; Membrane (Isoform 3); Membrane (Isoform 4); Membrane (Isoform 5)
Subcellular location (Human Protein Atlas): Nucleoplasm; Vesicles; Cytosol; Nucleoli fibrillar center
Gene Ontology:
Biological process: actin cytoskeleton organization
Cellular component: nucleoplasm; filamentous actin; microtubule organizing center; membrane; nucleus
Genetic constraint (gnomAD): Loss-of-function variants: 60 observed, 98.96 expected, observed/expected ratio (o/e) 0.61, 90% interval 0.49 to 0.75. The upper end of that interval is the gene's LOEUF score, 0.75, which puts it in group 3 of 6, group 1 being the genes least tolerant of losing a copy. Missense variants: 1,211 observed, 1,288.5 expected, observed/expected ratio (o/e) 0.94, 90% interval 0.9 to 0.99. Synonymous variants: 484 observed, 497.89 expected, observed/expected ratio (o/e) 0.97, 90% interval 0.9 to 1.05.
Homologues: Orthologues: chimpanzee SPECC1 (99% identical), macaque SPECC1 (98% identical), rabbit SPECC1 (87% identical), dog SPECC1 (87% identical), guinea pig SPECC1 (86% identical), rat Specc1 (85% identical), mouse Specc1 (85% identical), pig SPECC1 (77% identical), tropical clawed frog specc1 (61% identical), zebrafish specc1 (49% identical), Drosophila melanogaster spdi (26% identical). Paralogues in human: SPECC1L (40% identical).
Diseases named in the same sentence as SPECC1 in open-access papers:
SPECC1 is named in the same sentence as 28 diseases in open-access papers, as found by Europe PMC text mining. Sharing a sentence is not in itself a finding about the gene and the disease. The quoted sentences say what the papers report.
breast carcinoma (1 paper, 2021). "We furthermore identified upregulation of the direct EZH2 target genes CNN3 and AKAP13, that are involved in chemotherapy resistance in colon cancer and breast cancer, respectively, and the genes MYO5A, AKT3 and SPECC1, which are implicated in the evasion of apoptosis." (PMID 33712646, 2021).
gastric cancer (1 paper, 2025). A primary or metastatic malignant neoplasm involving the stomach. "Circ_SPECC1 was down-regulated in various gastric cancer cell lines." (PMID 40675967, 2025).
glioma (1 paper, 2025). A benign or malignant brain and spinal cord tumor that arises from glial cells (astrocytes, oligodendrocytes, ependymal cells). "For example, the circRNA-derived protein SPECC1-415AA regulates EGFR and restores sensitivity to TMZ in glioma cells." (PMID 40723354, 2025).
hepatocellular carcinoma (1 paper, 2022). A malignant tumor that arises from hepatocytes. "Moreover, circSLC8A1 has been linked to oxidative stress-related Parkinsonism, whereas circSPECC1, transcribed from Sperm Antigen with Calponin Homology and Coiled-Coil Domains 1 (SPECC1) is modulated upon H2O2 stimulation in hepatocellular carcinoma." (PMID 36428974, 2022).
cancer (5 papers, 2014 to 2021). A tumor composed of atypical neoplastic, often pleomorphic cells that invade other tissues. "We have found in previous studies that BCAP31 may regulate the migration and invasion ability of cancer cells by regulating the expression of cytoskeletal proteins, such as Drebrin, M-RIP, SPECC1, Nexilin, and F-actin." (PMID 32582765, 2020).
tumor (5 papers, 2016 to 2025). "Previous studies have verified that circSPECC1 functions as a tumor suppressor gene in GBM by encoding the protein SPECC1-415aa, and SPECC1-415aa can affect the sensitivity of GBM cells to TMZ." (PMID 39333871, 2024). "Apart from the known mutations, we report novel mutations in the genes AKT1, SPECC1, and LRP1B, which are linked with tumour progression and patient survival." (PMID 34796107, 2021).
SPECC1 also shares sentences with these, for which no sentence is quoted: infection (46 papers); COVID-19 (24); viral infection (22); Rotavirus infection (6); pancreatitis (2); adenoma (1); Alzheimer disease (1); bladder cancer (1); co-infection (1); cognition disorder (1); colon cancer (1); colorectal cancer (1); cross-infection (1); diarrhoea (1); endothelial dysfunction (1); epilepsy (1); gastroenteritis (1); glioblastoma (1); idiopathic generalised epilepsy (1); Parkinsonism (1); pneumonia (1); severe acute respiratory syndrome (1).